PDYN (prodynorphin)
Description:
Leu-enkephalins compete with and mimic the effects of opiate drugs. They play a role in a number of physiologic functions, including pain perception and responses to stress (By similarity). Dynorphin peptides differentially regulate the kappa opioid receptor. Dynorphin A(1-13) has a typical opioid activity, it is 700 times more potent than Leu-enkephalin (By similarity). Leumorphin has a typical opioid activity and may have anti-apoptotic effect.
Synonyms: PENKB; ADCA; SCA23
Tractability: Small molecule: a structure with a bound ligand is known. Antibody: its Gene Ontology location is reachable by antibodies, with high confidence; UniProt places it where antibodies can reach, with medium confidence; UniProt predicts a signal peptide or a membrane-spanning region. PROTAC: a small molecule that binds it is known.
Target class: Ion channel; Other ion channel; Pore-forming toxins (proteins and peptides)
Safety:
Unwanted effects reported when the protein is acted on. In parentheses: how it was acted on, where the effect was seen, and who reports it.
opioid dependence (source: ClinPGx)
Gene: Protein-coding gene on chromosome 20 (1,978,757 to 1,994,285, reverse strand). Ensembl gene ENSG00000101327.
Subcellular location: Secreted
Pathways (Reactome):
Signal Transduction: G alpha (i) signalling events; G-protein activation; Opioid Signalling; Peptide ligand-binding receptors
Gene Ontology:
Molecular function: protein binding; opioid peptide activity; opioid receptor binding
Biological process: neuropeptide signaling pathway; sensory perception of pain
Cellular component: hippocampal mossy fiber to CA3 synapse; neuronal dense core vesicle; plasma membrane; extracellular region; neuronal cell body; neuronal dense core vesicle lumen
Genetic constraint (gnomAD): Loss-of-function variants: 5 observed, 13.67 expected, observed/expected ratio (o/e) 0.37, 90% interval 0.19 to 0.77. The upper end of that interval is the gene's LOEUF score, 0.77, which puts it in group 3 of 6, group 1 being the genes least tolerant of losing a copy. Missense variants: 337 observed, 336.19 expected, observed/expected ratio (o/e) 1, 90% interval 0.92 to 1.1. Synonymous variants: 132 observed, 137.9 expected, observed/expected ratio (o/e) 0.96, 90% interval 0.83 to 1.11.
Homologues: Orthologues: chimpanzee PDYN (98% identical), macaque PDYN (95% identical), dog PDYN (78% identical), rabbit PDYN (77% identical), pig PDYN (76% identical), guinea pig PDYN (69% identical), rat Pdyn (65% identical), mouse Pdyn (64% identical), zebrafish pdyn (39% identical), tropical clawed frog pdyn (34% identical). Paralogues in human: PENK (28% identical), PNOC (13% identical).
Diseases named in the same sentence as PDYN in open-access papers:
PDYN is named in the same sentence as 71 diseases in open-access papers, as found by Europe PMC text mining. Sharing a sentence is not in itself a finding about the gene and the disease. The quoted sentences say what the papers report.
alcoholism (13 papers, 2012 to 2023). "PDYN down-regulation was found in people with a high-risk C allele of PDYN promoter SNP rs1997794 associated with alcoholism." (PMID 37509436, 2023). "Alcoholism and alcohol dependence are associated with several SNPs in the PDYN 5′-promoter, exons 3 and 4, and 3′-untranslated region (3′-UTR)." (PMID 34200173, 2021). "The exon 4 PDYN CpG island possesses a promoter activity, transcription factor binding sites, and the second cluster of TSSs, along with SNP associated with alcoholism." (PMID 34200173, 2021). "Human studies identified strong associations of SNPs in PDYN with alcoholism, drug addiction, emotions and memory." (PMID 34200173, 2021). "PDYN downregulation was confined to subgroup of subjects carrying C, a high-risk allele of PDYN promoter SNP rs1997794 associated with alcoholism." (PMID 29925858, 2018). "Our findings suggest that sex-dependent effects of PDYN variants in alcohol dependence are phenotype-specific." (PMID 26502829, 2015). "The discovery cohort had a larger sample size of cases (N = 816) and controls (N = 1248) to test associations between PDYN variants and alcohol dependence compared to the validation cohort (N = 467 and 431, respectively)." (PMID 26502829, 2015). "This network also includes PDYN (prodynorphin) which is of interest as it regulates alcohol consumption through dopamine neurotransmission and PDYN polymorphisms are linked to alcoholism as well as heroin and cocaine addiction in humans." (PMID 23555817, 2013). "Five PDYN SNPs are associated with alcoholism with high significance." (PMID 34200173, 2021). "Results presented here demonstrate that our previously reported findings of association between PDYN SNPs and haplotypes and alcohol dependence may be sex-related, and importantly, the sex-dependent effects are also trait (phenotype)-specific." (PMID 26502829, 2015). "Although speculative at this point, it is possible that the sex-related effects of the PDYN variants reported here are narrowing in on the genetic underpinnings of these particular subtypes of alcohol dependence." (PMID 26502829, 2015). "We also evaluated whether PDYN promoter variant rs1997794 associated with alcoholism affects PDYN expression." (PMID 26029055, 2015). "Our analysis of PDYN regulation in the brains of deceased human alcoholics demonstrated that three PDYN SNPs significantly associated with alcohol dependence form CpG sites, and that methylation of one of them was increased and positively correlated with DYN in alcoholics." (PMID 23060746, 2012). "We therefore examined whether adaptive PDYN responses to alcohol may be modulated by PDYN SNPs associated with alcoholism including promoter SNP rs1997794, and SNPs rs6045819 and rs2235749 located in coding exon 4 and 3′ untranslated region (3′-UTR) of the gene." (PMID 29925858, 2018). "Therefore, we here evaluated whether this SNP impacts changes in striatal PDYN expression associated with alcoholism." (PMID 26029055, 2015). "Therefore, it is possible that effects of PDYN variants on development of alcoholism and related phenotypes may also differ in males and females, resulting in SNP by sex interactions and sex-dependent genetic effects." (PMID 26502829, 2015). "Thus, a SNP in the promoter of PDYN is associated with alcohol-dependence and may impact PDYN transcription in human brain." (PMID 23060746, 2012). "Genetic studies associate polymorphisms in the PDYN gene and OPRK1, the KOR-encoding gene with heroin addiction, alcoholism, novelty seeking and positive reward traits." (PMID 34200173, 2021). "Thus, the environmental, epigenetic and genetic factors associated with alcoholism may be mechanistically integrated on the PDYN 3′-UTR CpG-SNP, and Ta-BF may read the resulting methylation signals and translate them into disease predisposition through changes in PDYN transcription." (PMID 34200173, 2021).
alcoholism (continued). "Effects of alcoholism on the whole tissue levels of PDYN and OPRK1 mRNAs in dlPFC were examined after adjusting for demographical data and tissue characteristics including age, PMI, brain pH, and RQI." (PMID 29925858, 2018). "Effects of PDYN and OPRK1 single-nucleotide polymorphisms (SNPs) strongly associated with alcoholism on expression of both genes were also studied." (PMID 29925858, 2018). "Effects of alcoholism on the whole tissue levels of PDYN, OPRK1, DRD1, and DRD2 mRNAs in NAc were examined after adjusting for demographical data and tissue characteristics including age, PMI, brain pH, and RQI." (PMID 29383684, 2018). "Previous studies found associations between the broad phenotype of alcohol dependence and sequence variation in human OPRK1 (encoding KOR) and PDYN genes." (PMID 24223163, 2013). "Alcoholism is associated with hypermethylation of the C allele of 3′-UTR CpG-SNP rs2235749 (C > T) in the human brain, and its methylation levels positively correlate with PDYN expression suggesting a functional link between these two processes." (PMID 34200173, 2021). "The PDYN rs2281285-rs1997794 haplotype is associated with alcoholism and susceptibility for drinking in negative emotional states." (PMID 34200173, 2021). "We next examined whether the tissue PDYN expression levels calculated as the ratio to reference genes were affected by alcoholism." (PMID 29925858, 2018). "Hypothetically, in alcoholics with high levels of PDYN and KOR expression, the increased DYN tone may result in attenuated dopaminergic transmission, produce depressive-like behaviors and dysphoria, and contribute to the increased alcohol consumption." (PMID 29383684, 2018). "Finally, we analyzed the expression of the brain-derived neurotrophic factor (BDNF)- tropomyosin receptor kinase B receptor (Trk-B) system as BDNF regulates ethanol intake by activation of downstream gene products like pDYN and is known to have a role in alcohol dependence vulnerability." (PMID 33671048, 2021). "We examined sex-dependent associations of PDYN variation with alcohol dependence and related phenotypes, including negative craving, time until relapse after treatment and the length of sobriety episodes before seeking treatment, in discovery and validation cohorts of European ancestry." (PMID 26502829, 2015). "We previously demonstrated that the PDYN promoter SNP rs1997794 associated with alcohol dependence may form non-canonical AP-1 binding site and influence gene expression in human brain." (PMID 26029055, 2015). "PDYN promoter SNP (rs1997794) associated with alcoholism may form non-canonical AP-1 binding site and influence gene expression in human brain." (PMID 26029055, 2015). "The findings of this study are intriguing, as the minor alleles of the PDYN SNPs rs2281285 and rs6132153 seem to have different effects on risk for alcohol dependence, negative craving and the length of sobriety before and after treatment for males and females." (PMID 26502829, 2015). "As reported in the previous publication, the association of the PDYN rs2281285 variant with the broader phenotype of alcohol dependence could not be found in the validation sample." (PMID 24223163, 2013). "Thus, under influences of the environment—heavy alcohol drinking-induced alterations in methylation of this SNP may affect PDYN transcription and, consequently, the vulnerability to develop alcohol dependence." (PMID 23060746, 2012). "The effect of alcoholism on the slope of the correlation between PDYN and OPRK1, manifested as significant alcoholism × OPRK1 interaction, suggests that alcoholics with high OPRK1 expression have greater PDYN mRNA levels than respective controls." (PMID 29383684, 2018). "PDYN mRNA significantly correlated with OPRK1 mRNA (P = 2 × 10−6), and there was a significant effect of interaction between alcoholism and PDYN–OPRK1 correlation (P = 0.011)." (PMID 29383684, 2018).
alcoholism (continued). "We first examined whether expression of PDYN and OPRK1—calculated for the whole tissue and also adjusted for changes in cell composition—was affected by alcoholism." (PMID 29383684, 2018). "The aim of the present study was to examine whether PDYN and PENK and their peptide products are involved in adaptive processes in the dorsal striatum in human alcohol dependent individuals." (PMID 26029055, 2015). "Thus, we examined whether transcription of the opioid PDYN and OPRK1 genes and dopamine receptor genes is coordinated in this neural microcircuitry, and if so, whether their co-expression patterns are affected by alcoholism." (PMID 29383684, 2018). "Moreover, conditioned place preference was absent in mice lacking the prodynorphin gene and mice administered norBNI; however, in that study, conditioned place preference was not tested in a model of alcohol dependence and the mice likely did not experience withdrawal." (PMID 27472317, 2016).
Anxiety (13 papers, 2011 to 2025). Intense feelings of nervousness, tension, or panic often arise in response to interpersonal stresses. "At least four prior studies used PDYN-deficient mice to evaluate the role of dynorphins in anxiety." (PMID 36768626, 2023). "Ayahuasca was demonstrated to attenuate anxiety-like behavior during ethanol withdrawal in mice, possibly by preventing ethanol-induced increase in 5-HT1a receptor and prodynorphin levels in the hippocampus." (PMID 40002450, 2025). "The distribution of dynorphin peptides and prodynorphin (PDYN) gene expression in the brain and spinal cord suggest their involvement in a large number of conditions, including stress and anxiety." (PMID 36768626, 2023). "PDYN gene knockout mice presented an increasingly explorative behavior in anxiety tests, which demonstrated the role of prodynorphin-derived peptides." (PMID 31510971, 2019). "On the other hand, the Pdyn knockout mice showed increased explorative behavior in anxiety tests suggesting an anxiogenic role of peptides derived from PDYN." (PMID 27275252, 2015). "Our data support previous data suggesting a pronounced impact of endogenous prodynorphin-derived peptides on anxiety." (PMID 22479578, 2012). "Data obtained from different strains of prodynorphin (Pdyn)- and kappa opioid receptor (KOP)-deficient mice do not provide a consistent picture of the functions of Dyn/KOP in anxiety, suggesting the influence of testing conditions and/or genetic background." (PMID 22479578, 2012). "Besides the debate on the role of dynorphins in anxiety, the adaptations occurring in stress-related molecular pathways following PDYN gene deletion are poorly understood." (PMID 36768626, 2023). "PDYN is a secreted opioid precursor of the central nervous system, and while PDYN-knockout mice are largely phenotypically normal, they do experience hyperalgesia and altered anxiety-related behaviors relative to wildtype mice." (PMID 36300623, 2022). "The mitigation of corticotropin releasing factor receptors and prodynorphin mRNA expression in zebrafish brain during the morphine withdrawal phase, indicates mitragynine's capability of reducing anxiety via the stress-related corticotropin pathway during opiate withdrawal." (PMID 32457670, 2020). "Furthermore, the loss of neuropeptides, such as NPY, PDYN and PENK, has also been associated with enhanced susceptibility to anxiety-like and depressive-like behavior in mice." (PMID 31251738, 2019). "Increased freezing in vmPFC PDyn shRNA mice during threat conditioning acquisition may stem from differences in locomotor activity, enhanced anxiety-like behavior, increased autonomic reactivity to threats, and/or increased working/short-term memory performance." (PMID 38283686, 2024). "Anxiety and stress‐coping ability, as well as working memory performance, were comparable among all groups tested (Fig EV4), suggesting no influence of pDyn overexpression." (PMID 31486590, 2019).
epilepsy (9 papers, 2016 to 2024). A brain disorder characterized by episodes of abnormally increased neuronal discharge resulting in transient episodes of sensory or motor neurological dysfunction, or psychic dysfunction. "The activation of KOPrs by prodynorphin (pDyn)-derived peptides has been implicated to control seizures in epilepsy." (PMID 39539623, 2024). "One or two repeats of 68bp named as L-allele, is associated with low PDYN expression, resulting in low prodynorphin level which increase susceptibility for epilepsy." (PMID 33096746, 2020). "In addition, lower prodynorphin expression due to mutations of promoter regions has been associated with increased susceptibility to epilepsy in people with a family history of TLE." (PMID 38249734, 2023). "In line with this, low prodynorphin levels, due to mutations in the promoter regions in humans, result in an increased vulnerability toward epilepsy." (PMID 28824375, 2017). "As previously discussed, there is likely to be a genetic element to epilepsy, which may involve opioid receptors, as mutations causing lower prodynorphin expression were demonstrated to correlate with increased susceptibility to epilepsy in people with a family history of TLE." (PMID 38249734, 2023). "DynB is one of the two major pDyn-derived products in the hippocampus and cortex, key sites in different types of epilepsy." (PMID 39539623, 2024). "To explore the in vivo role of PDYN in neuronal apoptosis in a rat model of pilocarpine-induced epilepsy, we injected PDYN-overexpressing lentiviruses and its control into the dorsal hippocampus of epileptic rats." (PMID 32206297, 2020). "As expected, compared with the LV-NC group, LV-PDYN administration significantly restored the reduction of PDYN mRNA and protein levels in the epilepsy model rats." (PMID 32206297, 2020). "Similarly, SNPs of key neuroregulatory genes were associated with TLE, including known epilepsy-associated genes NRG1, BDNF, or the PDYN promoter (prodynorphin;)." (PMID 38927072, 2024). "In most animal models of temporal lobe epilepsy (TLE; comprising epilepsies arising cortical = lateral TLE and mTLE), cortical and hippocampal prodynorphin expression is reduced after an initial, short peak of over‐expression." (PMID 26928671, 2016).
Parkinson disease (7 papers, 2011 to 2022). A progressive degenerative disorder of the central nervous system characterized by loss of dopamine producing neurons in the substantia nigra and the presence of Lewy bodies in the substantia nigra and locus coeruleus. "1-Methyl-4-phenyl-1,2,3,6-tetrahydropyridine (MPTP) and methamphetamine (MA), two commonly used neurotoxins in rodent models of Parkinson’s disease, were administered to wild-type (Dyn+/+) and prodynorphin-deficient mice (Dyn−/−)." (PMID 22695044, 2012). "For the first time MALDI-TOF imaging mass spectrometry (IMS) was used for unbiased assessment and topographical elucidation of prodynorphin-derived peptides in the substantia nigra of a unilateral rat model of Parkinson's disease and L-DOPA induced dyskinesia." (PMID 21984936, 2011). "Prodynorphin mRNA levels correlate well with the severity of dyskinesia in animal models of Parkinson's disease; however the identities of the actual neuroactive opioid effectors in their target basal ganglia output structures have not yet been determined." (PMID 21984936, 2011).
Dyskinesia (6 papers, 2011 to 2025). A movement disorder which consists of effects including diminished voluntary movements and the presence of involuntary movements. "Especially high striatal PDyn mRNA levels have been strongly associated with LID in animal models of dyskinesias and PD, including primates, monkeys and rodents." (PMID 21984936, 2011). "While there is a more specific association between high levels of PDYN mRNA and dyskinetic movements, on the other hand, high expression of PPENK mRNA is also correlated with locomotor hyperactivity, beyond dyskinesia." (PMID 30026724, 2018). "Changes in the striatal expression of proenkephalin and prodynorphin mRNA level have been reported in Parkinsonian rats with L-Dopa-induced dyskinesia." (PMID 29209553, 2017). "L-DOPA-induced dyskinesia in patients with PD has been linked to elevated preproenkephalin (PPE-A) and PDyn mRNA levels in the striatum." (PMID 21984936, 2011). "Traditionally the increase in PDyn mRNA is proposed to reflect an increased activity of striatonigral neurons of the direct basal ganglia pathway in dyskinesia." (PMID 21984936, 2011). "In the rat model of LID in experimental PD, the severity of dyskinesia correlates strongly with striatal prodynorphin (PDyn or PPE-B) mRNA levels." (PMID 21984936, 2011). "Moreover, higher PDYN mRNA expression in the lateral striatal portion of the DA-denervated hemisphere correlates only with the severity of dyskinesia, instead of with locomotor variables that define animals' spontaneous motion." (PMID 30026724, 2018).